ENSG00000293563 (novel protein)
Gene: Protein-coding gene on chromosome 12 (13,979,928 to 13,980,895, reverse strand). Ensembl gene ENSG00000293563.
Homologues: Orthologues: mouse Gm65988 (86% identical).